CD68 (CD68 molecule)
Diseases named in the same sentence as CD68 in open-access papers (continued):
Sharing a sentence is not in itself a finding about the gene and the disease.
tumor (continued). "Next, we stained ILT4 and CD68 (TAM marker) in sequential sections of 80 NSCLC tissues and found that patients with high ILT4 expression in tumor cells displayed markedly elevated CD68+ TAM infiltration." (PMID 33537094, 2021). "On the other hand, CXCL13 recruits CXCR5+ CD68+ macrophages secreting SPP1, which triggers tumor cell migration through the EMT pathway in lung cancer." (PMID 34947813, 2021). "Celecoxib in combination with IFNγ reduced the expression of MMP-2, MMP-9, and VEGF-A in tumor and decreased MVD, mediated by the increased amount of CD68+iNOS+ M1 macrophages and by decreased amount of CD68+Arg1+ M2 macrophages in mouse model of LLC." (PMID 34209679, 2021). "In the tumor capsule, 15% of dendritic cells, 55% of CD45 positive cells, 10% of CD11b positive cells, and 5% of CD68 positive cells were detected." (PMID 33921688, 2021). "CD3+, CD4+, CD8+, CD20+, CD57+, CD68+, and CD163+ cell infiltration was compared in samples from adjacent tissues and the tumor center." (PMID 33995627, 2021). "In this system, PDOs preserved fibroblast stroma that progressively decreased with the passages and contained CD3+ T cells in proximity to tumor epithelium, CD14+, CD68+ NK, and B cells." (PMID 34074330, 2021). "It has been reported that the most common tumor-infiltrating immune cells are CD8+ T cells and CD68+ M, accounting for 15% and 13% of all tumor cells, respectively." (PMID 33613757, 2021). "We performed immunohistochemical studies to assess the IL‐33, CD68 and CD206 levels in the tumour and non‐tumour tissue samples from patients with ESCC." (PMID 33305406, 2021). "Heatmaps show enrichment scores (NES) of GO pathways in primary tumors and LN metastases according to NE-low and NE-high phenotype, CD68+, CD163+, CD33+ cellular densities and MHCII-expression in tumor cells (in brief: macrophage-related parameters)." (PMID 34200100, 2021). "CD68 + TAMs make up 64% (NE-low) and 71% (NE-high) of CD45+ cells in tumor nests of primary tumors, while T-cells only represent 38% (NE-low) and 18% (NE-high) of immune cells." (PMID 34200100, 2021). "For this purpose, the mIHC panel was designed to simultaneously stain several markers including CD3 (for all T cells), CD8 (for cytotoxic T cells), CD68 (for macrophages), PCK (for tumor cells), and DAPI (for nucleic identification)." (PMID 34733790, 2021). "In the tumor capsule, 90% of dendritic cells, 55% of CD45 positive cells, 55% of CD11b positive cells, and 15% of CD68 positive cells were detected." (PMID 33921688, 2021). "IL‐33 is mainly located in the cytoplasm of ESCC cells, while CD68 and CD206 are mainly found in the tumour stroma." (PMID 33305406, 2021). "Enrichment of myeloid cells in tumor samples was also improved by IHC staining of the ECC tumor and paratumor sections with CD68 antibody." (PMID 33429363, 2021). "The immunofluorescent staining of our local clinical tumor tissue section analyses also showed that the expression of YAP1, LOX, CD68 (human macrophage marker), SPP1, and PD-L1 was enhanced in HSPA7-high GBM tissues compared to HSPA7-low tissues." (PMID 34354698, 2021). "Regression analysis showed a significant strong positive correlation between the cellular densities of CD3 + T-cells and CD68 + TAMs (r = 0.812) and CD163 + M2-polarised TAMs (r = 0.707) in tumor nests." (PMID 34200100, 2021). "Our antibody panel allowed the quantitation of immune cells actively involved in anti-tumor immunity and response, such as B-cells (CD20+), macrophages (CD68+) and distinct CD3+ T-cell populations." (PMID 34987518, 2021). "Another crucial finding shows that most CD68 + TAMs are M2-polarised, and express CD163 in NE-low tumor subsets, creating an immunosuppressive microenvironment peculiarly inside tumor nests." (PMID 34200100, 2021). "hrHPV+ tumors had markedly higher numbers of CD14+, CD68+ and CD163+ myeloid cells in the intratumoral tumor (IT Tumor) compartment compared to hrHPV− tumors (p=0.001, p < 0.001, p=0.002, respectively)." (PMID 34194435, 2021).
tumor (continued). "In our study, IPT-like FDCS tumor cells expressed CD21 and CD35, while partly expressing CD68, smooth muscle actin, vimentin, and clusterin." (PMID 33731032, 2021). "The TDLNs were collected from the IgG- or anti-4-1BB mAb-treated MC38 tumor-bearing B6 mice after the 4th injection of Abs, and the TDLN sections were stained with anti-CD68 mAb." (PMID 32868911, 2021). "The density of CD68+ macrophages was higher within and surrounding ISUP grade 4 index tumours than in ISUP grade 1 index tumours." (PMID 33330991, 2021). "While typical macrophage markers such as CD68, FCGR3A, MARCO, and CD14 were highly expressed in TAMs as well as non-tumor macrophage samples, the expression of canonical M1, M2, and TAM markers was more diverse." (PMID 33918618, 2021). "Significant differences in the mean preoperative tumor volume were also observed for all immune cell markers (CD3, CD8, CD68 and CD163)." (PMID 33530441, 2021). "hrHPV+ tumors had higher infiltration rates of CD14+, CD68+ and CD163+ myeloid cells in the IT tumor compartment (p < 0.001, for all) compared to hrHPV− tumors." (PMID 34194435, 2021). "We found CD68+, CD163+, CD206+, CD204+, and CHID1+ TAMs mainly distributed in the tumor stroma and tumor nest." (PMID 33466316, 2021). "In this study, we performed several immunohistochemical stainings, including S-100 protein, SOX-10, CD68, desmin, DOG-1, AE1/AE3, P63 and Ki-67, which are used as ancillary tests for diagnosis of the tumor." (PMID 34243786, 2021). "However, the role of CD68 in tumor-induced immune suppression remains unclear." (PMID 34079767, 2021). "Among the cytokines that correlate with CD68+ macrophages, IL-1β, IL-13 and VEGF have previously been described as tumor promoting factors." (PMID 34654395, 2021). "Immune cell infiltration was also detected in specific areas of the tumor tissue, showing infiltration of CD4+ T cells and CD68+ cells but rarely CD8+ T or B cells." (PMID 34070094, 2021). "Using immunohistochemistry, we evaluated CD169-expression on CD68-positive macrophages, and the density of CD8-postive lymphocytes in tumor microenvironment." (PMID 33816277, 2021). "In the tumor capsule, 85% of dendritic cells, 65% of CD45 positive cells, 65% of CD11b positive cells, and 10% of CD68 positive cells were detected." (PMID 33921688, 2021). "The correlation between CD68 and CD163 expression was significant and strong in tumor nests (r = 0.764) and moderate in the stroma (r = 0.455) CD33 expression showed significant correlation only with CD163 (r = 0.651 in stroma and r = 0.605 in tumor nests)." (PMID 34200100, 2021). "As TAMs always show M2‐like phenotypes, we measured CD68 (a total macrophage marker) and CD206 (an M2‐like macrophage marker) expression in the tumours and observed that both CD68 and CD206 expression can be inhibited by PGE3." (PMID 33982835, 2021). "Immunofluorescence showed that the proportion of CD68+ and CD163+ double-positive cells (M2 macrophages) infiltrating the tumor tissue of the experimental group was significantly higher than that in the control group." (PMID 34093541, 2021). "As reported in previous studies, the tumor was positive for immunomarkers CD31, CD34, D2-40, CD68, Ki-67 (1–2% positive nuclear staining) as well for smooth muscle markers SMA and Desmine." (PMID 34404967, 2021). "A total of 32 samples were selected for CD20, CD68, CD4, Foxp3, CD8, and P16 (for tumor cell staining) expression analysis by multiple immunofluorescence (mIF) staining and CD3 expression analysis by IHC staining." (PMID 35145511, 2021). "In the tumor capsule, 60% of dendritic cells, 35% of CD45 positive cells, 40% of CD11b positive cells, and 5% of CD68 positive cells were detected." (PMID 33921688, 2021). "In the tumor capsule, 70% of dendritic cells, 80% of CD45 positive cells, 80% of CD11b positive cells, and 15% of CD68 positive cells were detected." (PMID 33921688, 2021).
tumor (continued). "Instead, we found a tendency towards higher absolute macrophage infiltration (for both CD68+ and CD163+ cells) in the tumor core compared to the infiltration zone." (PMID 34654395, 2021). "M1 macrophages, highly expressed major histocompatibility complex class II, CD68 labeling and CD80/CD86 costimulatory molecules, located within tumors are thought to induce tumor suppression by activating anti-tumor immunity." (PMID 35284334, 2021). "On immunohistochemistry, the tumor cells showed positivity for ALK1 (nuclear), desmin, SMA, CD68, and focal positivity for CD30." (PMID 34249792, 2021). "Visualization of tumor-infiltrating immune cells confirmed that tNLR scores correlated directly with both neutrophil (CD15+ cells, rho 0.398, p = 0.0198) and macrophage (CD68+ cells, rho 0.515, p = 0.0018) cell counts." (PMID 33580206, 2021). "High CCL2 level also correlated with high CD68 and CD163 staining in tumor tissues, supporting the role of CCL2 in TAM recruitment." (PMID 34572939, 2021). "The density of CD14+, CD68+, CD163+ cells in the intratumoral tumor (IT Tumor) compartment was significantly higher in hrHPV+ tumors than in hrHPV− tumors (p < 0.001, p < 0.001, p < 0.001, respectively)." (PMID 34194435, 2021). "This analysis was conducted through a nearest-neighbor analysis of TMA tissues co-stained for pan-cytokeratin (tumor), CD8 (killer T-cells), CD68 (macrophages), and PD-L1 (immune checkpoint regulator)." (PMID 33526872, 2021). "In the present study, 269 advanced CRC lesions were immunohistochemically evaluated for CD47, SIRPA, CD68, and CD163 expression in tumor cells and TAIs." (PMID 33799989, 2021). "The best overall response rate and progression-free survival (PFS) were analyzed depending on the expression of CD68, CD163, PD-1, LAG-3, TIM-3, CTLA-4, TIGIT, CD163/c-maf in the tumor microenvironment in primary and sequential biopsies." (PMID 34830831, 2021). "Given the anti-tumour effect of MVC, its effect on polarization was investigated with respect to the TAM markers CD68 and YM-1." (PMID 34638423, 2021). "Recently, CD68 and CD163 were evaluated in both tumor nests and tumor stroma in 60 specimens of invasive breast cancer." (PMID 33968034, 2021). "The similar event happened in ESCC, for that CD68+PD-1+ TAMs in the ESCC TME are skewed toward an M2 phenotype, which can lead to elevation of tumor cell PD-L1 expression and promote tumor cell invasion and migration, associating with poor OS." (PMID 33995371, 2021). "(E) Patient tumor tissue stained by ISH for Cxcr3 and overlaying immunofluorescence for inflammatory (CD68+,iNOS+) macrophages." (PMID 34328416, 2021). "This is the reason that high tumor CD15 and CD68 expression indicates a limited response and poor survival." (PMID 34025640, 2021). "Thus high infiltration of M1 macrophages (CD68+iNOS+) in tumor islets was associated with increased overall survival (OS) in NSCLC, while high infiltration of total M2 macrophages (CD68+CD163+) in tumor islets and stroma was associated with reduced OS in NSCLC." (PMID 33194645, 2020). "The correlation of CD68+ and CD163+ macrophage infiltration with pathological features of the tumour was determined using Spearman’s correlations and Wilcoxon rank-sum tests." (PMID 32843682, 2020). "While nearly all MDCs were CD68+ for all cell lines, the percentage of CD163+ cells differed across the tumor lines." (PMID 33069212, 2020). "CD68− and CD206‐positive Mφ dominated the upper and central parts and were present both in the remaining Matrigel and intermingled with tumor cells that had invaded the CAM." (PMID 31825135, 2020). "The tumour-infiltrating immune cell densities, including CD8+ T cells, PD-1+CD8+ T cells and CD68+ macrophages were measured both in tumour nests and stroma using automated imaging analysis." (PMID 32235905, 2020). "The immune infiltrate of the OVC16 tumour contained B cells and macrophages; these were also detected in OvC-PDE culture, by IHC for CD20 and CD68, respectively." (PMID 33173111, 2020).
tumor (continued). "CD68 positive cells were positively correlated with TH (p = 0.0901) and DDC (p = 0.0168) immunoreactivity in tumor cells." (PMID 33244312, 2020). "Microglia/macrophages (CD68+) and T cells (CD4+ and CD8+) were still detected in the microscopically visible residual core of the tumor (Hoechst)." (PMID 33266255, 2020). "Remarkably, circulating class‐switched memory B cells (CD27+IgD−) showed a strong inverse correlation with CD68 staining grade, while intermediate monocytes (CD14++CD16+) negatively correlated with CD3+ and CD5+ cell density in the tumor." (PMID 33024560, 2020). "The third cluster (fC3, 56%) was dominated by the increased anti-tumor immune responses of CD3+; CD45ro+; and FoxP3+ TILs, CD68+ TAMs, as well as tumors of deep location." (PMID 32560244, 2020). "In the same study the infiltration of higher numbers of CD68+ or CD163+ macrophages in tumor stroma in BC patients didn’t depend on the OS, while infiltration in tumor nest was higher in patients with unfavorable OS." (PMID 33194645, 2020). "Sections from these biopsies were analyzed for the presence of tumor-infiltrating CD8+, PD-1+, CD68+ and CD163+ cells." (PMID 33344043, 2020). "The infiltration of different immune cell subpopulations; T cells (CD3), cytotoxic T cells (CD8), neutrophils (CD66b), macrophages (CD68), and B cells (CD20), was further evaluated at the tumor front using IHC staining, and the two groups were compared." (PMID 32290033, 2020). "This will be achieved via 1) assessment of the number of CD68 positive macrophages in tissue biopsies, 2) the expression levels of CD68 and CD20 proteins (by IHC) in tumor samples, and 3) the expression level of CD68-mRNA by Rt-PCR." (PMID 32019558, 2020). "An analysis of an inflammatory infiltrate of tumor stroma showed a correlation of CD68, iNOS and FOXP3 with a histological type of tumor." (PMID 32933105, 2020). "CD68 and CD163 positive macrophages were predominantly detected in the tumor stroma and intervening space between tumor cells." (PMID 33228719, 2020). "Despite these distinct tumor types, evaluation of RNA counts across samples for CD45 correlated with CD3E and with CD68 (p < 0.0001)." (PMID 33228231, 2020). "Consistent with RNA-seq analysis, the IR type showed several PD-1+CD8+ T cells and CD68+ type I macrophages infiltrating the tumour nest, while the XB and MS types showed scant CD8+ T cell infiltration in tumour nests." (PMID 32235905, 2020). "PD-L1 tumor cell expression was positively correlated with CD8+/GrB+ CTLs, FOXP3+ Tregs, PD-1+ T cells, and CD68+ TAMs." (PMID 32635549, 2020). "As for immunohistochemistry, all neoplasms stained positively for CD1a, CD207 (Langerin) and S100; inconstant was the stain for CD34 and CD68 (approximately 60%)." (PMID 32825016, 2020). "In contrast, M2-like macrophages, characterized by both CD68 and CD163 expression, are considered to promote tumor growth and metastasis by releasing chemokines, which are inflammatory growth factors." (PMID 32607685, 2020). "In this work, we used a semi-automated approach to quantify the CD8+, CD45RO+ and CD68+ infiltrates in both stromal and epithelial areas of primary HGSOC tumours." (PMID 32249277, 2020). "Stromal/tumoral expression of CD68 and CD163 was evaluated, as well as possible relationships with the expression of CSCs markers and tumor PD-L1." (PMID 32630659, 2020). "By flow-cytometry analysis of tumor-infiltrating cells (TICs) and lamina propria mononuclear cells (LPMCs) isolated from normal, adjacent mucosa of CRC patients, we showed that CD68/HLA-DRII-expressing TICs and LPMCs expressed M-CSFR-1." (PMID 33298879, 2020). "The expression level and in situ localization of miR-18a and -18b was assessed with respect to the presence of tumour infiltrating lymphocytes (TILs) and immunohistochemical markers for ER, CD4, CD8, CD20, CD68, CD138, PAX5 and actin." (PMID 32370743, 2020).
tumor (continued). "First, we tested for retention of tumor-resident T-cells (CD8), macrophages (CD68), and tumor markers, such as PD-L1 over the course of the ex vivo culture." (PMID 32554190, 2020). "CD68 and CD163 expression in tumor stroma were positively correlated with VEGF-A and VEGF-C in NSCLC patients’ tissues." (PMID 33228719, 2020). "We found that immune infiltration in the tumour microenvironment was continuously distributed across a wide range and CD8+, CD45RO+ and CD68+ infiltrates were strongly correlated." (PMID 32249277, 2020). "While, the CD163/CD68 + cells ratio as predictive index for a poorer prognosis of DLBCL is still controversial, M2 macrophages seems to have an active role in tumor progression in DLBCL patient." (PMID 32731512, 2020). "The density of total CD68+ TAMs and the proportion of CD68+/CD163+ TAMs were both statistically significantly lower in parenchymal (ie, epithelial) tumor areas compared with tumor stroma." (PMID 32190817, 2020). "Subsequently, we co-cultured FOXO1(+) tumor cells with M0 macrophages in the presence of the anti-CSF-1 antibody and found that a percentage of the CD163+/CD68+ macrophages was significantly reduced." (PMID 33052231, 2020). "The CD68, IL-6, and TNF-α expression in tumor cells was significantly higher in FOBT-positive patients than in FOBT-negative patients (all p<0.05)." (PMID 33643891, 2020). "Taking the optimised bespoke mIF detection algorithm, which extracts the phenotypic expression of PD-L1 in CK+ tumour cells only, after removing CD68+/PD-L1+ and CD8+/PD-L1+ cells, all 320 TMA cores were scored for PD-L1 tumour cell expression." (PMID 33374775, 2020). "This was necessary due to the proximity of the CD68 and CD8 cells to CK, which were often within the CK positive tumour epithelial nests." (PMID 33374775, 2020). "We found a significant positive correlation between NMU level and M2 percentage (CD206/CD68) in HCC peri- (r = 0.4624, p = 0.0302) and intra-tumor (r = 0.4448, p = 0.0381) tissue." (PMID 32013887, 2020). "By IHC analysis, we demonstrated that the expression levels of CD68, IL-6 and TNF-α in tumor cells of FOBT-positive patients were significantly higher than those in FOBT-negative patients." (PMID 33643891, 2020). "We used the median expression of CD68 and CD163 from the stromal samples to dichotomize the matched tumor samples." (PMID 32809114, 2020). "In comparison with tumor tissues from hormone-naïve prostate cancer patients, CRPC samples displayed higher number of CD68+ macrophages expressing cathepsin S enzyme known to be involved in angiogenesis and remodeling of extracellular matrix." (PMID 33194645, 2020). "Immunohistochemical staining of macrophages (CD68+ cells), p-BRD4 and CSF1 showed that macrophages were present in nearly all these implantation tumors, and p-BRD4 and CSF1 were expressed mostly in tumor cells." (PMID 32286255, 2020). "Cell densities were calculated for all biomarkers in both the intratumoral tissue and inside the IZ, which consists of three aspects: tumor (T), tumor edge (TE) and stroma (S); mean CD8+, CD20+ and CD68+ cell densities were calculated within each aspect." (PMID 33050344, 2020). "Image analysis automatically quantified CD68+, CD163+, and CD68+CD163− macrophage densities and CD3+ and CD8+ cells within the invasive margin (IM), tumor core (CT), and both IM and CT areas (IMCT) as well as TBs within the TB region of interest (TBROI)." (PMID 32435699, 2020). "This study thoroughly investigated the clinical relevance of TAM infiltration in OSCC, jointly evaluating CD68 and CD163 expression in both the tumor nests and surrounding stroma." (PMID 32630659, 2020). "KRAS mutated tumors had a significantly lower infiltration of NKp46+ NKT cells in the tumor and stromal compartments, and higher infiltration of NK cells, CD56+ NKT cells and CD68+ macrophages in the stromal compartment." (PMID 33013928, 2020).